CST3 (cystatin C)
Diseases named in the same sentence as CST3 in open-access papers (continued):
Sharing a sentence is not in itself a finding about the gene and the disease.
Hypertension (continued). "Apart from albuminuria and GFR, established or potential risk markers for diabetic nephropathy include hyperglycemia, hypertension, tubular injury markers, presence of specific urinary peptides, and serum cystatin C levels." (PMID 33203103, 2020). "Male gender, history of hypertension, highcreatinine, reduced triglycerides, high homocysteine, highusPCR, high cystatin C." (PMID 30281693, 2018). "Multivariate analysis, adjusted for sex, adiponectin, the liver-to-spleen ratio, DGLA and HOMA-R, revealed age, BMI, serum leptin level, the presence of hypertension and the cystatin C level to be positively related to EAT values." (PMID 28922364, 2017). "Altogether, we found nine genes (Cst3, Cyp11b2, Ephx2, Fn1, Igfbp2, P2rx4, Prkcd, RT1-Ba, and Sult1a1) annotated in the RGD as associated with hypertension in this group." (PMID 26822062, 2016). "Although the numbers are small, this suggests that those with albuminuria and cystatin C abnormalities tend to be older, male and a higher proportion have hypertension than those with albuminuria alone." (PMID 25700182, 2015). "Such early changes, detectable only through more sensitive markers like cystatin C, may precede hypertension or proteinuria, in line with the multistep progression described by the glomerular hyperfiltration hypothesis." (PMID 40622578, 2026). "The identified traits included lymphocyte counts, eosinophil counts, lymphocyte percentage (%) of white cells, eosinophil percentage (%) of white cells, coffee intake, pulse rate, hypertension, mean appendicular mass and levels of cystatin-C (a marker of kidney function)." (PMID 40963118, 2025). "In our logistic regression analysis, we adjusted for the duration of T2DM, duration of hypertension, systolic blood pressure, waist circumference, DR, diabetic neuropathy, HbA1c, fasting glucose, urea, creatinine, cystatin C, and urine albumin–creatinine ratio." (PMID 40076459, 2025). "Moreover, age, hypertension, diabetic retinopathy, eGFR, serum creatinine, cystatin C, calcium, hemoglobin, iPTH, albumin, LDL, IFTA, and arteriosclerosis were also significantly associated with adverse outcomes." (PMID 38571747, 2024). "Higher ln-serum cystatin C was significantly associated with increased OR of hypertension and a history of CVD, but not with other chronic diseases." (PMID 39859953, 2024). "In addition to stratification factors, we adjusted for age, CRP, eGFR, sex, HDL-c, LDL-c, UA, CLD, PLT, Cystatin C, hypertension, HBA1C, DM, CKD, smoking, and drinking status." (PMID 38402161, 2024). "In addition, cystatin C is closely associated with cardiovascular disease (CVD) risk factors, such as hypertension, aging, and diabetes." (PMID 37663661, 2023). "Hypertension and cystatin C could explain most of the sex differences in serum homocysteine levels in ACS subjects with normal serum creatinine." (PMID 37587534, 2023). "Plasma cystatin C had a higher explanatory value than hypertension in females." (PMID 37587534, 2023). "The differences in age (p = 0.001), hypertension (p < 0.001), cystatin C (p = 0.039), and FHS (p = 0.015) were statistically significant between the two groups, which means that age, hypertension, cystatin C, and FHS can be considered as risk factors for WMH in this study." (PMID 37239307, 2023). "In conclusion, hypertension and cystatin C could explain most of the sex differences in serum homocysteine levels in ACS subjects with normal serum creatinine." (PMID 37587534, 2023). "In the ESUS cohort, older age (62 vs 58, p = 0.014), and lower female incidence (30% vs. 42%), higher incidence of hypertension, higher glycated hemoglobin and cystatin c, more WMHs, lacunae and EPVSs, and higher CSVD burden were found in IAP compared to patients without." (PMID 37813922, 2023).
Hypertension (continued). "In males, a significant positive correlation was found between serum homocysteine (log10) and hypertension (r = 0.569, good correlation, P < 0.001), creatinine (r = 0.367, average correlation, P < 0.001) and cystatin C (log10) (r = 0.333, average correlation, P = 0.001)." (PMID 37587534, 2023). "In this study, we aimed to examine renal function, in particular the level of cystatin C, as an early predictor of kidney damage in patients with isolated arterial hypertension, those with comorbid pathology of hypertension and COPD, and those with isolated COPD." (PMID 36579215, 2022). "Therefore, this study used cystatin C to define ERI in patients with arterial hypertension and establish a relationship between qRSN and ERI." (PMID 35284141, 2022). "Additionally, we observed a significant effect of MetS (p = 0.006) and high blood pressure (p = 0.012) on the increase of cystatin C levels, and MetS (p = 0.024) and glucose (p ≤ 0.001) on the increase of CD14." (PMID 35846887, 2022). "Urea nitrogen was increased and cystatin C was reduced in COVID-19 patients with hypertension." (PMID 33557785, 2021). "Similarly, another study conducted in the city of Nanjing, China, demonstrated that BMI, nephritis, kidney neoplasm and hypertension were the key confounding factors affecting cystatin-C amongst the older adults." (PMID 34209146, 2021). "As people with low SEP tend to have a worse CVD risk profile including higher prevalence of smoking and high blood pressure, the role of these risk factors as mediators in a possible relationship between SEP and cystatin C as a marker of renal disease and predictor for CVD is of interest." (PMID 34588554, 2021). "However, cystatin C is influenced by factors such as age, body mass index, smoking, and levels of C reactive proteins, inflammation, hypertension, and cancer." (PMID 29096403, 2017). "Prevalence of cystatin C eGFR<60ml/min/1.73m2 was 7.7% and independently associated with age, lack of qualifications, being an ex-smoker, BMI, hypertension, and albuminuria." (PMID 25700182, 2015). "However, among the objects without hypertension, BMI < 24, renal disorder, and hyperuricemia, there were still lack of evidences showed that cystatin C level was significantly associated with severe plaque burden." (PMID 37817071, 2023). "In addition to periostin, literature retrieval and PCR verification were performed for other proteins that might be related to hypertension, such as Ahsg, Cst3, and Lrg1." (PMID 34084130, 2021). "Increased cystatin C levels are associated with carotid IMT in a multi-ethnic study on atherosclerosis, in the general population, in the health check-up population, in postmenopausal women, in metabolic syndrome patients, in patients with hypertension, and in patients with type 2 diabetes." (PMID 33129312, 2020). "Dependent factors included markers of hypertension (systolic and diastolic blood pressure) or CKD (creatinine, cystatin C, urinary albumin/creatinine), adjusted for body mass index." (PMID 40426748, 2025). "Cystatin C emerged as a better biomarker than serum creatinine as eGFR calculated from Cystatin C was above CKD stage 1 more consistently for all those that had an increased ACR, proteinuria or hypertension which are markers of abnormal kidney function." (PMID 39587464, 2024). "Through online searching IVs selected for serum cystatin C with Phenoscanner V2, we found several potential confounding phenotypes (e.g. BMI, SBP, DBP, log eGFR, hypertension, cholesterol)." (PMID 36482996, 2022). "As shown in the baseline characteristics of the Frequency of Renal Monitoring — Creatinine and Cystatin C (FORM-2C) population, the most common comorbidity in the cohort was hypertension, followed by formal diagnosis of CKD." (PMID 34048360, 2021).
Hypertension (continued). "Noteworthy, it has recently been published that in the Asian population, an elevated serum cystatin C level could also be considered as an independent predictor of cardiovascular events in subjects with normal renal function, as it has been demonstrated for age and hypertension." (PMID 24977136, 2014). "Parameters up to statistical significance in males or females, for example age, hypertension, LDL-C, ApoB, creatinine, cystatin C (log10) and UA, were incorporated into the stepwise linear regression models to determine which parameters were independently associated with homocysteine." (PMID 37587534, 2023). "Univariate logistic regression analysis showed that age, hypertension, SOFA score, and the levels of IL-6, WBC, NE, LYM, red blood cell, hs-CRP, DBIL, ALP, GGT, urea nitrogen, uric acid, cystatin C, sodium, chlorine, phosphorus and CK-MB were related to the aggravation of the patient's condition." (PMID 34397917, 2021). "Plasma cystatin C levels are increased by renal dysfunction and decreased in patients with aortic aneurysm and COPD patients often have comorbidities including cardiovascular and renal disease, hypertension, and cachexia." (PMID 27994288, 2016). "Interestingly, genetic associations with antibody-based circulating uromodulin at the PRKAG2 and UMOD/PDILT loci shared a very similar pattern of colocalization with numerous kidney-related traits (creatinine, cystatin C, urea, eGFR, CKD, urinary calculus, DBP, SBP, hypertension)." (PMID 35446786, 2022). "In the prospective analyses (age and sex adjusted) of the five individual components of MetS, baseline cystatin C was significantly related to incident abdominal obesity and incident elevated TG levels but not with incident hypertension, reduced HDL levels and incident hyperglycemia." (PMID 27218257, 2016). "Finally, among CST3 p.A25T homozygous carriers only 1/4 (25%) patients presented 3 moderate risk factors for SVID: hypertension, myocardial infarction and type 2 diabetes, 3/4 (75%) displayed hypertension and 1/4 (25%) did not present any risk factor for SVID." (PMID 32345996, 2020). "Finally, cystatin C may play a direct physiologic role and influence ventricular remodeling independent of hypertension and renal function." (PMID 21977320, 2011).
renal dysfunction (116 papers, 2005 to 2026). "Other studies have also shown that both renal dysfunction and cystatin C levels are risk factors for white matter damage." (PMID 40280803, 2025). "The AD_HI cluster was also associated with higher levels of AST and cystatin C, suggesting a general hepatic burden and possible subclinical renal dysfunction." (PMID 41357518, 2025). "The authors mentioned that the levels of urinary and serum cystatin C serve as useful markers for renal dysfunction in type 2 diabetes associated with normoalbuminuria." (PMID 39125705, 2024). "Simply speaking, the major risk factor for future cardiovascular events is renal dysfunction, and elevated cystatin C levels are only one manifestation of renal dysfunction." (PMID 35392813, 2022). "Less information is available on inequalities in biomarker levels indicating subclinical stages of disease such as cystatin C, an early diagnostic marker of renal dysfunction and predictor for cardiovascular disease." (PMID 34588554, 2021). "Regarding the predictive value of eGFR (based on cystatin C), it should be noted that aortic stenosis (AS) and renal dysfunction share risk factors and often occur simultaneously." (PMID 34946277, 2021). "EV levels of CD14 and Cystatin C are associated with both renal dysfunction and heart failure in patients presenting with dyspnoea at the emergency department." (PMID 32648717, 2020). "Regression analysis showed that Cystatin C was associated with renal dysfunction, heart failure, and their combination in all three EV sub‐fractions and in plasma." (PMID 32648717, 2020). "In this cross‐sectional cohort study, we showed that EV levels of CD14 and Cystatin C are associated with both renal dysfunction and heart failure in patients presenting with dyspnoea." (PMID 32648717, 2020). "High levels of Cystatin C were strongly associated with an increased risk of renal dysfunction in all three EV sub‐fractions in our study." (PMID 32648717, 2020). "The value of cystatin-C over estimated glomerular filtration rate for risk-stratification only emerged in patients with moderate renal dysfunction (eGFR 30–60 ml/min/1.73 m2, chi-square 12.9, P<0.001)." (PMID 23240006, 2012). "While guidelines recommend using eGFR based on both creatinine and cystatin C, our results underscore the importance of adopting sex-specific strategies for assessing and managing cardiorenometabolic risk in young adults with early renal dysfunction." (PMID 41200622, 2025). "Additionally, cystatin C, a marker of renal dysfunction, has been linked to impaired placental perfusion and increased oxidative stress in preeclamptic pregnancies." (PMID 40218901, 2025). "Cystatin C levels were also analyzed to determine their correlation with renal function tests to assess whether their levels were associated with renal dysfunction." (PMID 37569647, 2023). "In addition, renal dysfunction is associated with cardiac problems, which is linked to CVDs, and cystatin C concentrations are considered markers of renal function." (PMID 37663661, 2023). "As a key marker of renal function, cystatin-C may be closely related to MetS whereby patients carry high risk for CVD as well as renal dysfunction." (PMID 34209146, 2021). "Therefore, renal dysfunction was evaluated by measuring creatinine and urea as well as newer markers, i.e., cystatin C and neutrophil gelatinase-associated lipocalin (NGAL)." (PMID 32669536, 2020). "Cystatin C was associated with heart failure, renal dysfunction, and the combination of both conditions in all three EV sub‐fractions and in plasma, with the highest ORs for patients with both heart failure and renal dysfunction." (PMID 32648717, 2020). "In addition to CD14, we found that Cystatin C both in EVs and in plasma was associated with both renal dysfunction and heart failure." (PMID 32648717, 2020).
renal dysfunction (continued). "Thus, in this study, we aimed to investigate the association of renal dysfunction, using eGFR, proteinuria and cystatin C separately, with remote DWI lesions and total cSVD burden among the patients of primary ICH." (PMID 29930507, 2018). "However, it was associated with a reduced radiocontrast-induced renal dysfunction as assessed by cystatin C, a more sensitive and reliable parameter for estimating GFR early after CM exposure." (PMID 22938690, 2012). "The FANCY study further demonstrated that children with neonatal AKI and VLBW had a higher risk of renal dysfunction in childhood, particularly with sensitive biomarkers such as cystatin C-based eGFR and proteinuria, which may detect subclinical renal injury not captured by conventional markers." (PMID 40868470, 2025). "Cystatin C enabled earlier detection of renal dysfunction compared to serum creatinine, especially in preterm infants and critically ill neonates." (PMID 42072742, 2026). "Biomarkers such as cystatin C and neutrophil gelatinase-associated lipocalin (NGAL) have demonstrated clinical utility in detecting renal dysfunction earlier than traditional serum creatinine or urea-based assessments." (PMID 40978830, 2025). "Superior to creatinine, cystatin C detects early renal dysfunction unaffected by muscle mass or diet." (PMID 41169460, 2025). "Using cystatin C instead of creatinine to estimate eGFR results in a higher estimate of the prevalence of renal dysfunction." (PMID 39629062, 2024). "Other, less confounded, delayed, and sensitive parameters for renal dysfunction, such as cystatin C and urea levels, were already elevated at admission, demonstrating that the patients with sepsis were prone to experiencing renal dysfunction." (PMID 38892009, 2024). "In adults aged 18 to 50 years, baseline measurements indicated a higher prevalence of renal dysfunction when assessed using cystatin C compared to creatinine." (PMID 39629062, 2024). "Second, the adverse effects of higher concentrations of cystatin C in patients with CVDs cannot be completely attributed to renal dysfunction." (PMID 37663661, 2023). "Cystatin C is an endogenous lysosomal cysteine protease inhibitor, and serum cystatin C can be used as a marker for the diagnosis of renal dysfunction." (PMID 37497234, 2023). "Apart from renal dysfunction, cystatin C has been proposed to be a predictor of cardiovascular disease (CVD) and all-cause mortality, including that due to CVD." (PMID 37569647, 2023). "There were weak inverse correlations between plasma vitamin C and specific markers of renal dysfunction, including cystatin C, serum creatinine, and urine albumin (p < 0.01)." (PMID 35204128, 2022). "In our included studies, we also found a significantly higher rate of renal dysfunction in the high serum cystatin C population than in the low serum cystatin C population." (PMID 35392813, 2022). "In future studies, we would like to examine the albuminuria and cystatin C levels, which are markers of renal insufficiency, to have a more global exploration of the factors at play in maternal renal dysfunction during pregnancy." (PMID 36614889, 2022). "The concentrations of calretinin and mesothelin increased with increased cystatin C reflecting renal dysfunction." (PMID 34768395, 2021). "In this research, the levels of serum uric acid, urea nitrogen, creatinine, cystatin C and eGFR were detected and renal dysfunction was evaluated among COVID-19 patients between on admission and discharge." (PMID 33557785, 2021). "Here, we found that elevated ACR, serum urea, creatinine, and cystatin C, markers of the severity of renal dysfunction in DN, were decreased by SCFAs." (PMID 32831998, 2020). "The primary aim of this study is to investigate the association between the selected EV proteins (Cystatin C, CD14, SerpinG1, and SerpinF2) with both renal dysfunction and heart failure in patients with acute dyspnoea." (PMID 32648717, 2020).